EXT1 (exostosin glycosyltransferase 1)
Diseases named in the same sentence as EXT1 in open-access papers (continued):
Sharing a sentence is not in itself a finding about the gene and the disease.
acute lymphoblastic leukemia (8 papers, 2016 to 2025). Leukemia with an acute onset, characterized by the presence of lymphoblasts in the bone marrow and the peripheral blood. "EXT1 is a tumour suppressor gene that has downregulated expression in acute lymphoblastic leukaemia and is frequently hypermethylated in leukaemia, causing the loss of heparan sulphate synthesis." (PMID 37756103, 2023). "A second report, from Japan, described a 14-month-old boy with pre-B acute lymphoblastic leukemia and an EXT1 deletion." (PMID 41441317, 2025). "It is reported that miR-665 promotes cell proliferation and suppresses apoptosis in acute lymphoblastic leukemia by suppressing EXT1." (PMID 33858426, 2021). "Moreover, it is reported that EXT1 promoter hypermethylation was detected in many types of cancers, including non‐melanoma skin cancer and leukaemia, especially acute promyelocytic leukaemia and acute lymphoblastic leukaemia." (PMID 33565239, 2021). "EXT1 is hypermethylated in leukemia (especially acute promyelotic leukemia and acute lymphoblastic leukemia) and nonmelanoma skin cancer in a screen of 454 primary tumors of different types and 79 human cancer cell lines, implying that epigenetic regulation of EXT1 is linked to oncogenesis." (PMID 28672878, 2017).
Langer-Giedion syndrome (7 papers, 2008 to 2026). "Langer–Giedion syndrome (LGS), also known as Trichorhinophalangeal Syndrome Type II (TRPSII) (OMIM 150230), is a rare contiguous gene syndrome caused by a deletion involving loss of functional copies of TRPS1 and EXT1." (PMID 32296131, 2020). "Langer-Giedion syndrome (LGS) or TRPS type II is a contiguous gene syndrome on 8q24.1, involving loss of functional copies of the TRPS1 and EXT1 genes." (PMID 26269715, 2015). "Six probes were screened in the 8q24 region associated with Langer-Giedion syndrome, in TRPS1 (2 probes), EIF3S3 (1 probe), EXT1 (2 probes) and SAMD12 (1 probe)." (PMID 18925931, 2008). "Langer-Giedion syndrome (LGS), also known as trichorhinophalangeal syndrome type II (TRPS II; OMIM #150230), is a contiguous-gene deletion disorder caused by haploinsufficiency of TRPS1 and EXT1." (PMID 41751561, 2026). "TRPS type 2 or Langer-Giedion syndrome (OMIM #150230) involves TPRS1, RAD21 and EXT1, and the facial phenotype is mainly determined by loss of TRPS1, whereas the bony abnormalities arise from the loss of EXT1." (PMID 32193685, 2020). "A deletion in chromosome 8q24.11 or 8q23.3-q24.13, which contains EXT1, but not TRPS1, also causes Langer-Giedion syndrome." (PMID 34539746, 2021).
leukemia (7 papers, 2010 to 2023). A malignant (clonal) hematologic disorder, involving hematopoietic stem cells and characterized by the presence of primitive or atypical myeloid or lymphoid cells in the bone marrow and the blood. "For example, gene expression of EXT1 was found to be abrogated in human cancer cells and epigenetic loss of EXT1 in leukemia and non-melanoma skin cancer was linked to CpG island hypermethylation, resulting in loss of HS." (PMID 32937952, 2020). "It was shown that epigenetic inactivation of EXT1, leading to an abrogation of HS biosynthesis, is common for leukemia and non-melanoma skin cancer, and reintroduction of EXT1 into HS-deficient leukemia cells HL-60 suppressed colony formation and growth of tumour xenografts." (PMID 20723247, 2010). "In leukemia and non-melanoma skin cancer cells, epigenetic inactivation of EXT1 by promoter hypermethylation is found and the tumor suppressing effect of Ext1 was revealed." (PMID 36809261, 2023).
multiple myeloma (7 papers, 2013 to 2025). "In one report, knockdown of EXT1 in multiple myeloma cells suppressed tumor growth, resulting in a significantly extended survival in animal model." (PMID 31200735, 2019). "The relevance of regulated enzymatic activity for proteoheparansulfate synthesis has been demonstrated by knockdown of EXT1 also involved in the chain elongation of heparan sulfate chains leading to reduced growth and increased apoptosis in myeloma cells." (PMID 24386263, 2013). "However, in multiple myeloma, the correlation of high expression of EXT1 and a poor prognosis was reported." (PMID 36809261, 2023). "Furthermore, HS chains are reported to be crucial for the growth and survival of multiple myeloma (MM) cells and in vivo knockdown of EXT1 was verified for the suppression of its growth, implicating the possible role of EXT1 in cancer progression." (PMID 29050299, 2017). "The biological and clinical importance of genes involved in heparan- and chondroitin-sulfate synthesis is emphasized by our findings of EXT-1 heparan sulfate copolymerase (EXT1) being an adverse prognostic factor, and is critical for in vitro and in vivo growth of multiple myeloma." (PMID 24386263, 2013). "In previous report, EXT1 has been reported as to enhance canonical WNT signalling activity during chondrogenic differentiation, in addition, knock‐down of EXT1 using CRISPR/Cas9 resulted in aberrant WNT signalling in multiple myeloma." (PMID 33565239, 2021).
exostoses (6 papers, 2014 to 2022). "She suffered from exostosis, which are explained by the known EXT1 variant NM_000127.2 (EXT1): c.538_539delAG (p.Leu181Profs*7)." (PMID 34479984, 2021). "The EXT1 variant is also present in her father whose sole symptoms consist of an exostosis phenotype." (PMID 34479984, 2021). "Hereditary multiple exostoses is a relatively frequent autosomal dominant bone disorder resulting from heterozygous inactivating mutations of EXT1 and EXT2 genes." (PMID 24532482, 2014). "It is intriguing, however, that single Ext1 knockout mice fail to gastrulate, whereas the loss-of-function mutations of human homolog EXT1 show incomparably milder phenotype (multiple hereditary exostosis)." (PMID 29962964, 2018). "Considering that dominant mutations in EXT1 and EXT2 genes cause hereditary multiple exostoses and the EXTL1 gene is expressed at very low levels in brain cells, EXTL2 and EXTL3 represent the most promising candidates in this pathway for SRT." (PMID 32121121, 2020). "To the best of our knowledge, no patients, other than patient 2 with exostosis, have been reported until now, and we did not analyse patient 2 for the presence of an additional genetic defect, in particular for EXT1 or EXT2 mutations." (PMID 31555217, 2019).
Obesity (6 papers, 2017 to 2025). Accumulation of substantial excess body fat. "Additionally, EXT1 at 8q24.11 is associated with obesity and PDZRN4 at 12q12 is associated with BMI and skin pigmentation." (PMID 30946739, 2019). "To confirm the robustness of our finding we also examine the impact of total loss of adipocyte HS chain generation on diet-induced obesity (DIO) and type-2 diabetes susceptibility by genetically targeting Exostosin 1 (EXT1)." (PMID 41072794, 2025). "EXT1 (ENSP00000367446), encoding a member of transmembrane glycosyltransferase has been reported to participate in the obesity associated biological processes in the Lebanese Arab population." (PMID 29258237, 2017). "Ap2-Cre mediated Ext1 deletion in macrophages is likely not contributing to the reduced weight in Ext1flox/+Ap2-Cre+ mice that decreased HS sulfation in macrophages promotes obesity and insulin resistance." (PMID 41072794, 2025).
cartilaginous tumors (5 papers, 2011 to 2022). "Moreover, the participation of some genes involved in cartilaginous tumors was also observed, such as inactivating mutations in exostosin-1/2 (EXT1/EXT2) genes." (PMID 34069269, 2021). "Grade 1 tumors often have mutations in the SDH gene family (central atypical cartilaginous tumors mostly IDH1 and 2, secondary peripheral atypical cartilaginous tumors mostly EXT1)." (PMID 35681674, 2022).
Autoimmunity (4 papers, 2021 to 2025). The occurrence of an immune reaction against the organism's own cells or tissues. "These patients were carefully screened and followed up, and none was found to have a tumor, suggesting that EXT1/EXT2 and THSD7A may be associated with autoimmunity." (PMID 39927251, 2025).
benign bone tumors (4 papers, 2017 to 2024). "However, EXT1 is well-defined as a tumor suppressor in benign bone tumors, ER-negative tumors, and tumors of patients with successively developed distant metastasis have high levels of EXT1 expression." (PMID 29050299, 2017).
Bone tumors (4 papers, 2010 to 2022). "In this case, palovarotene is directed at benign bone tumors that characterize EXT1/EXT2-CDG, and a trial is being conducted in mice modeling this phenotypic feature." (PMID 35955863, 2022).
Enchondromatosis (4 papers, 2011 to 2024). Enchondromatosis is a rare primary bone dysplasia disorder characterized by the development of multiple mainly unilateral or asymmetrically distributed enchondromas throughout the metaphyses of the long bones. "Functional mutations in the exostosin genes (EXT1 and EXT2) are reported to affect the hedgehog signalling pathways leading to multiple enchondromatosis." (PMID 36676722, 2022). "Unlike enchondromatosis, EXT-1 and EXT-2 mutation (exostosin protein) is not observed in metachondromatosis." (PMID 39027184, 2024).
hepatocellular carcinoma (4 papers, 2002 to 2021). A malignant tumor that arises from hepatocytes. "In hepatocellular carcinoma, increased copy number of EXT1 results in more mRNA abundance and thus predicted a shorter disease‐free survival rate without vascular invasion." (PMID 33565239, 2021). "Hepatocellular carcinoma (HCC) cells exhibited EXT1-mediated activation of TGF-β-enhancing chemosensitivity to 5-FU, implicating its role in the augmentation of EMT features." (PMID 29050299, 2017).
lupus nephritis (4 papers, 2021 to 2026). Glomerulonephritis in the context of systemic lupus erythematosus. "The IgG1 dominance for anti-NCAM-1 antibodies shares similarity with anti-EXT1/EXT2 antibodies, supporting the association of both NCAM-1 and EXT1/EXT2 with lupus nephritis." (PMID 33808418, 2021). "Approximately 1/3 of patients with class V lupus nephritis are positive for EXT1/EXT2 and the same percentage of mixed class lupus nephropathy (class III/IV with class V)." (PMID 36016931, 2022). "Similar to the association of EXT1 and EXT2 with lupus nephritis, NCAM-1 was reported as an antigen for membranous lupus nephritis (MLN) and PMN." (PMID 33808418, 2021). "For instance, the EXT1/EXT2-related MN with class V lupus nephritis, MN with undetermined antigen associated with no associated diseases." (PMID 36016931, 2022).
Sepsis (4 papers, 2018 to 2025). Sepsis is defined as life-threatening organ dysfunction caused by a dysregulated host response to infection. "Exostosin-1 (EXT-1) participates in the synthesis and reconstruction of glycocalyx, but this process is delayed in sepsis." (PMID 40799817, 2025). "Exostosin-1 (EXT-1), a heparan sulfate elongation gene, is involved in glycocalyx synthesis and restitution, which is delayed in sepsis." (PMID 34217286, 2021). "Previous studies has reported that enhancing endothelial fibroblast growth factor receptor 1 signaling improves EXT-1-mediated pulmonary glycocalyx reconstitution in sepsis." (PMID 34217286, 2021). "In sepsis, EXT-1 expression is decreased, and glycocalyx reconstitution is delayed, which increases sepsis severity." (PMID 34217286, 2021). "The results showed that, compared with the healthy control group, the expression of EXT1, HIF1A and HMMR was upregulated in sepsis, whereas the expression of CD44, EXT2 and SELL was downregulated in sepsis group." (PMID 40672940, 2025). "Herein, we found that PCTR1 unregulated EXT-1 expression and downregulated HPA expression, promoting glycocalyx reconstitution in sepsis model via ALX receptor consequently." (PMID 34217286, 2021).
cholangiocarcinoma (3 papers, 2017 to 2018). A carcinoma that arises from the intrahepatic biliary tree (intrahepatic cholangiocarcinoma) or from the junction, or adjacent to the junction, of the right and left hepatic ducts (hilar cholangiocarcinoma). "Recently, EXT1 was found to be elevated in plasma of human cholangiocarcinoma patients and proposed to be the prognostic marker for cholangiocarcinoma." (PMID 30054430, 2018). "Recently, however, EXT1 was found to be elevated in the liver and plasma of an animal model of cholangiocarcinoma (CCA)." (PMID 28672878, 2017).
glioblastoma (3 papers, 2017 to 2023). The most malignant astrocytic tumor (WHO grade IV). "A pro-tumorigenic activity of EXT1 has been reported in a glioblastoma model, since EXT1 knockout reduced cell proliferation in vitro and growth of glioblastoma xenograft in mice by attenuating receptor tyrosine kinase activity." (PMID 36982528, 2023). "We generated endothelial cell-specific knockout of Ext1, a gene encoding a glycosyltransferase and essential for HS synthesis, and murine GL261 glioblastoma cells were orthotopically transplanted." (PMID 34790962, 2021).
glioma (3 papers, 2017 to 2026). A benign or malignant brain and spinal cord tumor that arises from glial cells (astrocytes, oligodendrocytes, ependymal cells). "The study findings identified EXT1 as a central glycosylation-linked regulator of replication stress tolerance and immune remodeling in gliomas, and suggest that EXT2 contributes to extracellular matrix and cytoskeletal reprogramming." (PMID 41438585, 2026). "While inactivating mutations in EXT1/2 are well-documented in hereditary exostoses 10, their functional roles in cancer 11, 12, and in gliomas specifically, remain poorly defined." (PMID 41438585, 2026). "Such enrichment is consistent with the observation that EXT1-high gliomas exhibit resistance to genotoxic agents, likely through enhanced tolerance to replication stress." (PMID 41438585, 2026). "Representative IHC images showed minimal EXT1 expression in low-grade gliomas, whereas high-grade tumors exhibited strong cytoplasmic staining, predominantly localized to non-neuronal stromal regions rather than neuronal compartments." (PMID 41438585, 2026). "Immunohistochemistry on a glioma tissue microarray validated the upregulation of EXT1 protein in high-grade tumors." (PMID 41438585, 2026). "By aligning multi-omic signals with niche topology, the EXT1 or EXT2 axis model offers a rigorous template for glyco-oncology in glioma and a roadmap for prospective validation in organoids, patient-derived xenografts, and early translational research." (PMID 41438585, 2026). "By addressing these questions, our study provides one of the first molecular and spatially resolved characterizations of the EXT1/2 axis in gliomas." (PMID 41438585, 2026). "While both EXT1 and EXT2 were found to be upregulated in gliomas, we prioritized EXT1 for immunohistochemical (IHC) validation due to its stronger transcriptomic association with immune suppression, stromal activation, and clinical outcomes." (PMID 41438585, 2026). "Exostosin glycosyltransferase 1 (EXT1) and exostosin glycosyltransferase 2 (EXT2) catalyze heparan sulfate chain elongation and are increasingly implicated in cancer biology, but their roles in gliomas remain incompletely defined." (PMID 41438585, 2026). "Bulk transcriptomic data from The Cancer Genome Atlas (TCGA) and the Chinese Glioma Genome Atlas (CGGA) revealed that both EXT1 and EXT2 are upregulated in high-grade gliomas and associate with adverse survival, with EXT1 showing the strongest and most consistent prognostic impact." (PMID 41438585, 2026). "To further elucidate the molecular contexts of EXT1 and EXT2, we constructed PPI networks using STRING based on their top co-expressed genes in gliomas." (PMID 41438585, 2026). "EXT1 expression significantly varied by WHO grade, with higher levels observed in high grade gliomas." (PMID 41438585, 2026). "We then analyzed the expression patterns of EXT1 and EXT2 across clinical and molecular subtypes in the CGGA glioma patient cohort." (PMID 41438585, 2026). "To further investigate upstream mechanisms driving their dysregulation, we next analyzed the DNA methylation landscapes of EXT1 and EXT2 in TCGA gliomas." (PMID 41438585, 2026). "The novelty of this study lies in revealing that EXT1 and EXT2, traditionally viewed as redundant HS polymerases, are in fact spatially partitioned regulators of glioma aggressiveness." (PMID 41438585, 2026). "Here, we performed an integrative multi-omics analysis to dissect the transcriptional, epigenetic, and microenvironmental landscape of EXT1 and EXT2 across gliomas." (PMID 41438585, 2026). "To further characterize the divergent oncogenic roles of EXT1 and EXT2, we performed a GSEA on glioma cohorts stratified by high versus low expression of each gene." (PMID 41438585, 2026). "To further validate and investigate the functional divergence between EXT1 and EXT2, we performed genome-wide co-expression analyses using TCGA-Glioma transcriptomic data." (PMID 41438585, 2026).
glioma (continued). "Among the 33 tumor types analyzed, EXT1 and EXT2 were significantly upregulated in all primary glioma samples relative to normal brain samples, a pattern similarly observed in several other tumor types." (PMID 41438585, 2026). "Given their consistent dysregulation and biological relevance, EXT1 and EXT2 were selected as the principal isoforms for downstream multi-omics analyses in gliomas." (PMID 41438585, 2026). "These insights support the potential of EXT1 and EXT2 as predictive biomarkers and targets for rational drug design in gliomas." (PMID 41438585, 2026). "EXT1-high tumors may be vulnerable to synthetic lethality approaches involving checkpoint inhibition (CHK1 or ATR inhibitors), whereas EXT2-driven gliomas might respond to combinatorial regimens targeting cytoskeletal remodeling or focal adhesion dynamics 73-75." (PMID 41438585, 2026).
Intellectual disability (3 papers, 2021 to 2025). "Six patients with pathogenic variants in EXT1 showed intellectual disability (low CI), normal brain image and karyotype." (PMID 36360300, 2022). "Six patients, with EXT1 pathogenic variants, presented intellectual disability and/or behavioral problems." (PMID 36360300, 2022). "In the clinical context, autosomal dominant mutations of EXT1 causing familial exostosis were reported in two unrelated subjects with hereditary multiple exostoses, ASD, and intellectual disability." (PMID 39859496, 2025). "Recent studies report skeletal involvement together with other clinical manifestations including dysmorphism or multiple congenital anomalies and various degrees of developmental delay/intellectual disability including an EXT1 MO patient." (PMID 36360300, 2022).
lung carcinoma (3 papers, 2021 to 2024). "In that study, the authors found that A549 lung cancer cells were scattered located inside the spheroid if surrounded by mutated fibroblasts with reduced Ext1 expression (Ext1Gt/Gt)." (PMID 39011470, 2024). "We overexpressed Ext1 in 293T-ACE2 cells to assess the functional consequence of upregulated Ext1 expression in the vulnerability of lung cancer to SARS-CoV-2." (PMID 34179075, 2021). "In this study, we uncovered that the expression of several HS biosynthetic genes, including Ext1, is upregulated in lung cancer." (PMID 34179075, 2021). "Consequently, administration of ω‐3 PUFAs may be potentially effective in counteracting the EXT1 methylation‐mediated lung cancer‐promoting effects." (PMID 33565239, 2021). "The Ext1 overexpressing 293T-ACE2 cells showed higher infection of SV-2S pseudovirus than the scrambled control, suggesting the Ext1 upregulation may be one of the mechanisms underlying the higher susceptibility of lung cancer patients to SARS-CoV-2 infection." (PMID 34179075, 2021).